POSTN (periostin)
Diseases named in the same sentence as POSTN in open-access papers (continued):
Sharing a sentence is not in itself a finding about the gene and the disease.
asthma (continued). "Although shown to be related to the T2 pathway in severe asthma periostin proved to be outside of the T2 cluster in patients with moderate asthma." (PMID 41602869, 2026). "Although periostin has been studied in asthma and chronic rhinosinusitis, its role in allergic rhinitis (AR) and nasal hyperresponsiveness (NHR) is unclear." (PMID 41683582, 2026). "As a result, this study established 2 definitions of “type 2–low asthma” using serum periostin and IL4RA for endo-genotyping and POSTN and IL4RA for genotyping." (PMID 40687950, 2025). "This study aims to evaluate serum periostin’s utility in diagnosing asthma and distinguishing disease severity in a South Indian cohort, contributing valuable insights for resource-limited settings." (PMID 41374409, 2025). "In individuals with asthma, periostin levels are often increased, especially in those with eosinophilic inflammation and severe disease." (PMID 40649123, 2025). "In the Firth-penalized logistic regression model, periostin was the only significant predictor of asthma diagnosis (β = 0.387, OR = 1.47; 95% CI: 1.23–2.08; p < 0.001)." (PMID 41374409, 2025). "We identified 8 key genes (LOC100132287, CEACAM5, PRR4, CPA3, POSTN, LYPD2, TCN1, and SCGB3A1) associated with asthma by combining the LASSO regression model and the SVM-RFE method." (PMID 39963184, 2025). "The clinical utility of periostin is also being investigated in other inflammatory diseases, including chronic kidney disease, asthma and rheumatoid arthritis." (PMID 41226478, 2025). "In support of this, prior studies have demonstrated the synergistic role of TSLP alongside other Th2 inflammation markers, such as Periostin and blood eosinophil counts, in stratifying asthma severity and predicting treatment response." (PMID 40503233, 2025). "Periostin is a protein that plays a significant role in the pathogenesis of asthma, particularly in severe asthma and airway remodeling." (PMID 40649123, 2025). "Serum periostin levels were significantly elevated in both asthma groups compared with healthy controls [moderate: 51.1 (48.8–52.8) pg/mL; severe: 52.5 (48.6–56.4) pg/mL vs. controls: 35.5 (25.1–40.8) pg/mL; p < 0.001]." (PMID 41374409, 2025). "By targeting the pathways involved in periostin expression and airway remodeling, these biologic therapies offer a more focused approach to asthma management." (PMID 40649123, 2025). "Each 1 pg/mL rise in periostin increases the log-odds of asthma by 0.387; therefore, a 10 pg/mL elevation, well within the typical biological range, would increase the odds of asthma by almost four-fold." (PMID 41374409, 2025). "Biologic agents, including monoclonal antibodies targeting interleukin-13 (IL-13) such as dupilumab, have shown efficacy in reducing periostin levels and improving asthma control in patients with severe eosinophilic asthma." (PMID 40649123, 2025). "Together, these analyses highlight that multidimensional unsupervised clustering can identify clinically relevant asthma phenotypes based on combined periostin, inflammatory, demographic, and functional parameters within this population." (PMID 41374409, 2025). "This cross-sectional study confirms that serum periostin is a robust and reliable biomarker for asthma diagnosis among adults in a South Indian cohort." (PMID 41374409, 2025). "The primary endpoint was the asthma exacerbation rate in periostin-high (≥50 ng/mL at baseline) versus periostin-low (<50 ng/mL) groups, which was not significant." (PMID 40863432, 2025). "In distinguishing asthma severity, ROC analysis showed limited discriminatory power for periostin (cut-off of 53.208 pg/mL, sensitivity of 46.2%, specificity of 80.0%, AUC of 0.562) (Figure 3A1)." (PMID 41374409, 2025). "Cluster 3 (n = 11) was marked with intermediate age (median 40 years), mixed asthma severity, highest periostin levels (median 53.1 pg/mL), elevated BMI, and pronounced systemic inflammation (NLR 5.1, PLR 200, SII 1247)." (PMID 41374409, 2025).
asthma (continued). "Through network pharmacology analysis and animal experiments, FEO‐03 was found to inhibit the Th2‐related inflammatory and fibrotic responses in airway tissues via regulation of periostin/TGF‐β signaling pathway in asthma." (PMID 40777200, 2025). "Measuring periostin levels in the blood or sputum can serve as a biomarker for eosinophilic inflammation and airway remodeling in asthma." (PMID 40649123, 2025). "Established biomarkers, including serum immunoglobulin E (IgE), blood eosinophils, the fraction of exhaled nitric oxide (FeNO), and serum periostin, helped elucidate the complex pathophysiology of the eosinophilic type 2 (T2) asthma endotype." (PMID 40863432, 2025). "The study also found that FEO‐03 reduced the expression of fibrotic markers through the periostin/TGF‐β signaling pathway in asthma." (PMID 40777200, 2025). "POSTN promoted mucin hypersecretion and sustained eosinophilic inflammation, both of which were essential pathologies of asthma." (PMID 41142810, 2025). "Periostin has been identified as an effective serum biomarker for several diseases, most recently for pulmonary diseases such as asthma." (PMID 39940700, 2025). "In contrast, select investigations describe increasing periostin levels upon worsening asthma severity or poor disease control, albeit often confounded by heterogeneous patient selection or co-existing comorbidities." (PMID 41374409, 2025). "Serum periostin is generated by airway epithelial cells in response to IL-13 and is a marker of T2-related airway inflammation in patients with asthma." (PMID 40863432, 2025). "Elevated serum periostin levels correlate with asthma severity and subphenotypes such as eosinophilic inflammation." (PMID 41278223, 2025). "Given periostin’s integral role in asthma pathophysiology, it has emerged as a promising biomarker reflecting airway inflammation and remodeling." (PMID 41374409, 2025). "Periostin, in turn, has been reported to be elevated in the serum of children with asthma, supporting its utility for diagnosis and patient stratification." (PMID 40981017, 2025). "Firth regression identified periostin as the only independent predictor of asthma diagnosis (β = 0.387; OR = 1.47; 95% CI 1.23–2.08; p < 0.001)." (PMID 41374409, 2025). "In their study, the researchers found that asthma patients showed distinct activation of the epithelial genes periostin (POSTN), chloride channel regulator 1 (CLCA1), and serpin peptidase inhibitor clade B member 2 (SERPINB2) when compared to healthy controls." (PMID 41303221, 2025). "In vitro and in vivo studies have also reported a significant upregulation of periostin in pathological states characterized by inflammation, fibrosis, and dysregulated angiogenesis, e.g. allergy, asthma, and cancer." (PMID 40053143, 2025). "Beyond diagnosis and severity, periostin’s most transformative impact lies in its integration into asthma phenotyping and personalized management." (PMID 41374409, 2025). "Among them, periostin (gene name: POSTN) is a matricellular protein that is involved in diverse inflammatory responses in asthma, including the development of the Th2 phenotype." (PMID 40777200, 2025). "The serum periostin concentration is a biomarker for ECRS with asthma, and it is correlated with the Lund–Mackay score." (PMID 38785953, 2024). "Periostin is secreted by lung fibroblasts of individuals with asthma and acts as an adhesion molecule, binding other extracellular matrix proteins and resulting in subepithelial fibrosis." (PMID 38690264, 2024). "Quantitative PCR was used to monitor the impact of storage conditions on the expression of housekeeping genes: GAPDH and β-actin, and the asthma related genes: POSTN and FBN2." (PMID 38948078, 2024). "A low level of transcription from the periostin gene (PSTN) was observed, a gene that has been associated with TH2 high asthma." (PMID 38201301, 2024).
asthma (continued). "Periostin plays a crucial role in tissue remodeling and inflammation and has emerged as a potential prognostic factor for asthma." (PMID 38474348, 2024). "The findings revealed elevated periostin levels in severe asthma patients compared to those with mild to moderate asthma and healthy controls." (PMID 39195245, 2024). "The findings demonstrate that CDC167, POSTN, SEC14L1, and SERPINB2 exhibit potential as diagnostic markers and therapeutic targets for individuals with asthma." (PMID 38580753, 2024). "Recognition of serum biomarkers, such as periostin, which has been identified as a biomarker for type 2 inflammatory airway disease, is valuable for diagnosing asthma and specifying its phenotypes or endotypes." (PMID 39534447, 2024). "POSTN promoted mucin hypersecretion and sustained eosinophilic inflammation, both of which were essential asthma pathologies of asthma." (PMID 38580753, 2024). "In respiratory diseases, periostin is recognized to be contributed in the development of asthma and IPF." (PMID 38370408, 2024). "Periostin, an extracellular matrix protein, plays a role in airway remodeling in eosinophil-predominant asthma and is known to be a biomarker of eosinophilic inflammation or type-2-mediated immune responses and airway remodeling in bronchial asthma." (PMID 38785953, 2024). "The effect of lebrikizumab on asthma exacerbation in biomarker-high patients with severe asthma (periostin ≥50 ng/mL or blood eosinophils ≥300 cells/μL) was later examined in phase 3 trials, LAVOLTA I and LAVOLTA II." (PMID 38785953, 2024). "Periostin was highly expressed in the lungs of patients with idiopathic pulmonary fibrosis, similar to that in patients with asthma." (PMID 39534447, 2024). "In this context, our study group examined periostin concentrations in the airways of severe asthma patients, particularly focusing on the type-2 (T2) immunity endotype, using EBC and induced sputum." (PMID 39195245, 2024). "Clinically, periostin is useful for phenotyping asthma, particularly for monitoring inflammatory responses and exercise-induced bronchoconstriction." (PMID 39534447, 2024). "Similar interactions between periostin and integrins have been observed in airway epithelial cells, where they play a role in tissue remodeling in both CRSwNP and asthma." (PMID 39728072, 2024). "Specific treatments such as omalizumab, Lebrikizumab, and Tralokinumab have been effective in decreasing the periostin levels in the airways, suggesting their potential role in managing asthma-related tissue remodeling and inflammation." (PMID 38474348, 2024). "In contrast, serum periostin levels, while valuable in understanding systemic changes, are more prone to variability possibly due to other comorbidities such as asthma, allergic rhinitis and atopic dermatitis." (PMID 39728072, 2024). "Due to the absence of non-asthmatic AR control participants, it was challenging to delineate the specific impact of AR versus asthma on the elevated levels of periostin and YKL-40 as observed in our study." (PMID 39534447, 2024). "Jia et al16 identified periostin as a systemic biomarker for airway eosinophilia in asthmatic patients, suggesting its potential use in selecting patients for new asthma treatments targeting Th2 inflammation." (PMID 39534447, 2024). "Sputum eosinophilia was not correlated with other biomarkers, including peripheral blood eosinophilia, FeNO, and serum periostin, a finding that has been also reported in other studies of pediatric asthma." (PMID 39685659, 2024). "CXCL12 has been shown to participate in inflammatory response and airway remodeling in both OVA- and HDM-induced asthma models, while POSTN was confirmed to be upregulated in epithelial and subepithelial layers in bronchial biopsies of asthmatics." (PMID 38317239, 2024).
asthma (continued). "Sputum samples derived from three severe asthma patients (#4 - #6) with high sputum periostin levels measured by Assay A and Assay B showed clear bands corresponding to both the monomeric form and the cleaved product." (PMID 36763690, 2023). "Similar tissue alterations are present in other Th2 pathway-mediated disorders such as asthma, in which serum periostin reflects inflammation activity, thus, it serves as a biomarker of acute flare of the disease." (PMID 37773198, 2023). "IL-13 also plays a major role in the secretion of periostin (POSTN), which is an essential biomarker in asthma." (PMID 36832296, 2023). "Periostin is also implied in asthma airway remodeling, as it promotes activation of fibroblasts and has autocrine effects on the epithelial cells." (PMID 37108417, 2023). "In the current investigation, initially aimed at method development, it was also possible to compare serum and sputum periostin measurements in clinical cohort of patients with asthma." (PMID 36763690, 2023). "Correlations between serum and sputum periostin and clinical characteristics in patients with asthma from BIOAIR study." (PMID 36763690, 2023). "Previous studies in adults have shown that POSTN and several other genes can be used to define subsets with T2-high and T2-low asthma." (PMID 36776870, 2023). "As a biomarker, higher levels of periostin correlate with higher exacerbation rate and poor asthma control." (PMID 37108417, 2023). "Periostin is relatively stable with little variation, and a strong correlation between FeNO and serum periostin levels has been observed in severe asthma." (PMID 38203353, 2023). "It is higher in atopic patients than in nonatopic patients and can be considered a diagnostic biomarker of bronchial asthma, but the exact role of periostin as an asthma predictor remains controversial." (PMID 37629446, 2023). "On the contrary, significant differences in serum periostin levels were found according to asthma endotypes, with the highest levels in patients with AERD, which is consistent with data obtained in other studies." (PMID 37744693, 2023). "In fact, higher nasal periostin levels were significantly related to lower frequency of current asthma at age 4, ever diagnosis of asthma, maintenance asthma treatment prescription, and admissions for recurrent wheezing." (PMID 36694181, 2023). "In view of the contradictory data and the limited evidence available, it seems that the role of periostin in the development of asthma in children with a history of severe bronchiolitis is far from being clarified." (PMID 36694181, 2023). "Periostin is a distinct signature protein for the T2-high asthma phenotype in adults although its role in children is controversial." (PMID 36694181, 2023). "The severe asthma endotype is currently defined by biomarkers of varying accuracy including blood and sputum eosinophils, periostin, FeNO, and IgE for T2 asthma." (PMID 36675122, 2023). "Since serum periostin was found to be relatively unsuccessful in identifying an asthma population that particularly benefit from anti-IL-13 treatment, interest in periostin as a phenotype-specific biomarker has been somewhat reduced." (PMID 36763690, 2023). "Using a more extensive algorithm that included blood eosinophil counts, serum periostin and FeNO levels also led to a greater decrease in corticosteroid dose than treatment guided by asthma symptoms, lung function and recent exacerbation history." (PMID 40980110, 2023). "Potentially this study will contribute to finding a more accurate cut-off level of periostin for non-T2 asthma, as evidence in previous studies are conflicting." (PMID 37794472, 2023). "The effect of a 2-week oral corticosteroid intervention was examined in a subset of asthma patients and was found to significantly reduce sputum periostin levels to a greater degree than observed in matched serum samples." (PMID 36763690, 2023).
asthma (continued). "Some studies have found higher levels of serum periostin in children with asthma and some of them even reported a significant correlation between serum periostin levels and asthma severity." (PMID 36694181, 2023). "Less is known about sputum periostin as a biomarker in asthma as detection levels are low using currently available periostin assays." (PMID 36763690, 2023). "The objectives of this study were to assess the stability of these phenotypes and the correlation between serum periostin and asthma T2 phenotypes and endotypes." (PMID 37744693, 2023). "Although serum POSTN is associated with type 2 inflammation in the airways of patients with asthma, systemic POSTN levels are derived from multiple sources, including age, body mass index, and bone formation." (PMID 38020106, 2023). "Serum periostin levels in asthma patients decrease in response to therapy with systemic or inhaled corticosteroids." (PMID 37046572, 2023). "The main goal of this study was to investigate the association of nasal detection of periostin and thymic stromal lymphopoietin (TSLP) during severe bronchiolitis with the development of asthma at 4 years of age." (PMID 36694181, 2023). "As sputum cytokines were not investigated as part of the BIOAIR study, we carried out an additional investigation into the relationship between sputum periostin with sputum IL-4 and IL-13 in a separate cohort of patients with asthma." (PMID 36763690, 2023). "Initial investigations of sputum periostin as a biomarker in asthma have all described relatively low detection levels in this matrix, sometimes below the lower detection limits of the assays used." (PMID 36763690, 2023). "Patients with high serum levels of periostin had a greater improvement in lung function and reduced asthma exacerbations following treatment with the anti–IL-13 lebrikizumab." (PMID 37035303, 2023). "Currently, a few clinical biomarkers for asthma are available, including eosinophils, neutrophils, IgE, FeNO, leukotrienes, and periostin." (PMID 38203353, 2023). "Peripheral eosinophilia, blood level of periostin, fractional concentration of exhaled nitric oxide (FeNO), and allergen-specific IgE levels have been used as surrogates for sputum eosinophils in asthma." (PMID 37511786, 2023). "This study combines a panel of non-T2 inflammatory markers (low periostin, low blood-eosinophils, and low FeNO), to determine if this group of patients can maintain asthma control during ICS withdrawal." (PMID 37794472, 2023). "Periostin is involved in different inflammatory conditions such as asthma, atherosclerosis, rheumatoid arthritis, and other skin diseases, such as atopic dermatitis." (PMID 37773198, 2023). "In a 52-week RCT of tralokinumab, another anti-IL13 mAb, significant improvements in asthma exacerbation rate, lung function, and asthma symptoms were also found in patients with increased pre-treatment periostin serum levels." (PMID 36226150, 2022). "For instance, higher levels in FeNO, blood eosinophils, and serum periostin (Th2-high asthma) are indications for use of the IgE antibody Omalizumab." (PMID 36078171, 2022). "POSTN (a known biomarker for asthma) was upregulated in the mixed group compared to asthma and lung cancer samples." (PMID 35406434, 2022). "Serum periostin is an established biomarker of Th2 driven immunoreaction in asthma and allergic dermatitis." (PMID 35850759, 2022). "Periostin promotes inflammation and fibrosis in different disease states including myocardial infarction, idiopathic pulmonary fibrosis, asthma, skin scleroderma, hepatic fibrosis, muscular dystrophy and chronic renal disease." (PMID 35707463, 2022). "In another recent study it was noted that periostin is a good marker of eosinophilic inflammation in patients with asthma." (PMID 35327702, 2022). "In asthma, periostin is recognized as a biomarker of type 2 inflammation and periostin (POSTN) gene expression is up-regulated in bronchial epithelial cells by IL-13 and IL-4." (PMID 36010292, 2022).